EPCAM (epithelial cell adhesion molecule)
Diseases named in the same sentence as EPCAM in open-access papers (continued):
Sharing a sentence is not in itself a finding about the gene and the disease.
cancer (continued). "Firstly, only cancer indications which express EpCAM in > 90% of cases should be considered." (PMID 34715784, 2021). "Moreover, there have been several reports that combined EpCAM aptamer as targeting element with MSNs to enhance the cytotoxic effects of anti-cancer drugs against CRC cells." (PMID 34641857, 2021). "Cancer tissues of epithelial origin often overexpress EpCAM." (PMID 33919456, 2021). "As so, the expression of the cancer markers epithelial cell adhesion molecule (EpCAM) and CD147 in taMPs was shown to be specific of cancer patients, which could potentially be used for diagnostic purposes." (PMID 33673461, 2021). "EpCAM has been reported to play an important role in cancer development." (PMID 34790117, 2021). "EpCAM has been proposed as one of the cancer stem cell (CSC) markers." (PMID 34021129, 2021). "Interestingly, HER3 is highly expressed in cancer cells (CD45−/EpCAM+/E-CAD+), but limitedly in T cells (CD45+/CD8+/CD4+)." (PMID 33888713, 2021). "To analyze somatic EpCAM mutations in human cancers, we queried the COSMIC database as well as 178 non-redundant datasets including 47,005 samples in the cBioPortal for Cancer Genomics." (PMID 33980181, 2021). "All salivary lymphocytic cells were removed by antibodies conjugated to magnetic beads in the device, and the precancer and cancer cells were then captured and enriched using antibodies (conjugated to magnetic beads) specific for dysplasia and cancer (e.g., EpCAM)." (PMID 34359370, 2021). "Epithelial cell adhesion molecule (EpCAM) is a cancer-related antigen." (PMID 33919456, 2021). "As expected, WT and cancer-associated EpCAM mutants expressed at the cell surface suppressed invasion, while cancer-associated EpCAM mutants with no expression at the cell surface did not affect invasion." (PMID 33980181, 2021). "The EpCAM-independent subtraction enrichment (SE) is irrelevant to both hypotonic hemolysis and microfludic’s shear stress, which helps maintain high viability of cancer cells." (PMID 34680256, 2021). "Moreover, it is reported that positive EpCAM expression rate ranges 37–42.3% of the various cancers with FDA-approved Cell Search system." (PMID 34112129, 2021). "Our platform was proven to have high specificity and sensitivity for the detection of rare CTCs in the blood sample of HCC patients, and further comparison was carried out with the separation ability of EpCAM and Vimentin, which are universal types of pan-cancer." (PMID 33726759, 2021). "However, EpCAM is frequently present as a monomer under different experimental conditions, and EpCAM is known to be cleaved and secreted by cancer cells as shown by us and by others." (PMID 33980181, 2021). "Hence, EpCAM downregulation during mesodermal differentiation in ESCs and during EMT in carcinoma cells is linked to enhanced endocytosis and a block or reduction of its recycling to the plasma membrane." (PMID 34693227, 2021). "Mutations in the EPCAM gene have been linked to Hereditary Non-Polyposis Colorectal Cancer, which is a well-known cancer susceptibility syndrome that predisposes to many types of cancer, particularly, colorectal adenocarcinoma and endometrial carcinoma." (PMID 32212818, 2020). "Furthermore, EpCAM remains an attractive target for antibody-based cancer therapies and as a biomarker for patient stratification." (PMID 32507912, 2020). "Moreover, soluble EpCAM was also investigated because there is considerable evidence suggesting that this plays an important role in the progression of many cancers." (PMID 32039729, 2020). "EpCAM has recently been recognized as a surface marker of cancer stem cells (CSCs)." (PMID 32212818, 2020). "Therefore, most of the EPCAM-positive cells were likely cancer cells due to the presence of copy number changes." (PMID 33083004, 2020).
cancer (continued). "Due to a high and stable expression of EPCAM in primary cancers, adenocarcinomas, metastases and malignant effusions and cancer stem cells, including circulating cancer stem cells, it could be used as a biomarker." (PMID 33027913, 2020). "CTC clinical applications in various cancer types have been validated by EpCAM-based technologies." (PMID 32764280, 2020). "EpCAM-selectivity also significantly limits the effectiveness of cancer stem cell detection." (PMID 31936460, 2020). "Therefore, a high abundance of EpCAM in cancer will result in more EpICD being released into the cytoplasm, thus upregulating the expression of these important cell cycle regulators that will subsequently promote cell growth and tumourigenesis." (PMID 32046162, 2020). "EpCAM is essential for carcinogenesis in numerous types of human cancer." (PMID 33154781, 2020). "EpCAM’s ability to stimulate tissue plasticity is likely to be an important facet of the role of EpCAM in cancer, and the next major challenge will be to build on the knowledge obtained from embryonic tissue to define the morphogenetic potential of EpCAM during cancer development and metastasis." (PMID 32961790, 2020). "EpCAM is expressed in epithelial tissues, progenitor cells, cancer cells, and stem and germ cells." (PMID 32493501, 2020). "A long literature implicates TROP2 and EpCAM in cancer biology." (PMID 32781650, 2020). "EpCAM+ and Vimentin+ aneuploid CTCs and CTECs, produced by the transdifferentiation of CSCs or heterotypic cell fusion of cancer cells with ECs, were detected in cancer patients with a variety of epithelial carcinomas." (PMID 32599893, 2020). "Therefore, it provides evidence that EpCAM is important for the diagnosis and treatment of these types of cancers." (PMID 32714406, 2020). "Therefore, it is of high interest to study glycosylation of EpCAM or perhaps other types of post-translational modifications that contribute to the onset of cancer." (PMID 32046162, 2020). "In other words, the heterogeneity in cancer molecular subtypes might limit the generalization of the importance of EpCAM expression and CTCs in clinical studies." (PMID 32764280, 2020). "Moreover, cell surface markers such as CD24, CD26, CD44, CD90, CD133, CD166, CD177, aldehyde dehydrogenase 1 (ALDH1), and epithelial cell adhesion molecule (EPCAM) have been identified as biomarkers of CSCs in various types of cancers." (PMID 33014829, 2020). "However, EpCAM+ mammary progenitor cells give rise to chromosomally unstable cancers, such as triple-negative basal-like/postepithelial mesenchymal transition and HR+ cancers." (PMID 33020483, 2020). "This review will focus on the structure-features of EpCAM protein and discuss recent evidence on the pathological and physiological roles of EpCAM in modulating cell adhesion and signalling pathways in cancers as well as deliberating the clinical implication of EpCAM as a therapeutic target." (PMID 32046162, 2020). "Moreover, EpCAM is reported to be involved in the spread of breast as well as retinoblastoma cancers." (PMID 32391048, 2020). "Thus, the CSC markers, CD44, CD44v6, CD44v8-10, and EpCAM have the potential to predict cancer recurrence including CCA." (PMID 32039729, 2020). "When analyzing the co-expression pattern for these two markers inside the CD45-negative subset, we watched CK (+) EpCAM (-) population underwent the largest increase with disease progression from CIN to cancer (with the peak at stage IA), with CK (+) EpCAM (+) cell counts being also elevated." (PMID 32899940, 2020).
cancer (continued). "This suggests that EpCAM+ CTCs and DTCs could be reliable biomarkers for evaluating therapeutic efficacy and predicting cancer prognosis." (PMID 32764280, 2020). "Soluble CD44, CD44v6, CD44v8-10 and EpCAM are promising factors for predicting cancer recurrence." (PMID 32039729, 2020). "CTCs in the blood could be readily characterized by the presence of EpCAM, which is the epithelial marker, and highly expressed in the cancers of epithelial origin." (PMID 32046162, 2020). "However, there are unavoidable problems with this approach, the reliance on EpCAM and CK presence and the variation in their expression among the different types of cancer and the different stages is a major drawback for these modalities." (PMID 32708837, 2020). "Obviously, collecting exosomes of specific origin not only facilitates the study of their parental cells, but also provides important indicators for disease diagnosis (for example, via detecting EpCAM positive exosomes to assess the existence of EpCAM related cancers)." (PMID 32206116, 2020). "Even assuming that the role of EpCAM is solely restricted to moderating cortical tension, it may have different effects on invasion, depending on the type of cancer and on the context." (PMID 32961790, 2020). "EpCAM can be downregulated when cancer cells undergo the epithelial-mesenchymal transition (EMT)." (PMID 32493501, 2020). "In summary, this study shows that similar to radioresistant BC cells, EpCAM overexpressing cells show high degree of plasticity and heterogeneity which ultimately induces radioresistant and metastatic behavior of cancer cells, thus aggravating the disease condition." (PMID 33490064, 2020). "In effector cells harvested from ascites of patients suffering from EpCAM-positive cancers, the bAb has further been shown to induce effector cytokines such as interferon-γ and upregulation of surface-expressed CD107a indicative of cytotoxic granule release in both CD4+ and CD8+ T cells." (PMID 32438548, 2020). "In addition, immunocytochemical analysis of the association between endogenous EpCAM expression and reporter EGFP labeling further supported that KiPCs are cancer-like cells." (PMID 33233448, 2020). "EpCAM is strongly expressed not only on cancer cells, but also on stem cells." (PMID 32764280, 2020). "As their number in blood can vary among patients with the same cancer type, selecting patients based on the EpCAM+ CTC count in the peripheral blood could be a better and more precise way to identify patients who could benefit from such therapies." (PMID 32764280, 2020). "This reflects the high specificity of EpCAM among cancer subjects." (PMID 32212818, 2020). "CellSearch is the only CTC isolation method approved by the U.S. Food and Drug Administration (FDA) for cancer prognosis and it is based on the immunological interaction between epithelial cell adhesion molecules (EpCAM) on CTCs and anti-EpCAM immobilized on magnetic particles." (PMID 32848184, 2020). "EpCAM has a dynamic expression among CTCs of different origins and at different cancer stages; it becomes highly downregulated when CTCs disseminate from primary sites and undergo epithelial-to-mesenchymal transmission (EMT) to acquire a more aggressive phenotype and seed for metastasis." (PMID 32708837, 2020). "Therefore, the Fc-fusion strategy has also been applied to the EpCAM-Fc fusion cancer vaccine expressed in insect and plant systems." (PMID 33143243, 2020). "However, EpCAM antibody is only specific for a few types of tumor cells, and considering the high heterogeneity of cancer, it cannot be used as a universal biomarker." (PMID 32121271, 2020). "Therefore, EpCAM can be detected in CTCs and also in circulating exosomes isolated from the blood of patients with cancer." (PMID 32764280, 2020). "This may result in a decrease in EpCAM+-CTCs and an increase in EpCAM−-CTCs counts when a patient’s cancer is progressing." (PMID 32071283, 2020).
cancer (continued). "Subsequent study has shown that CAR T cells targeting EpCAM on human ovarian and colorectal cancer cells are capable of killing the cancer cells in vitro, and the adaptive transfer of these CAR T cells prolonged the animal survival by eliminating the established ovarian xenografts." (PMID 32391048, 2020). "The Parsortix system that isolates CTCs based on their size and deformability showed higher isolation efficiency compared to the EpCAM-dependent enrichment method of CellSearch® in the case of Hs746T and C32 cancer cell lines (p-value = 2.63 × 10−5 and 2.90 × 10−7, respectively)." (PMID 32102486, 2020). "We believe that such knowledge will not only provide us with a better understanding of this major EpCAM signaling pathway, but also pave the way for new possibilities for a rational design of the next-generation of drugs for treating carcinomas and other diseases involving EpCAM." (PMID 32486423, 2020). "Additionally, EpCAM was found to be hyperglycosylated in carcinoma tissue as compared to autologous normal epithelial." (PMID 32046162, 2020). "EpCAM was originally recognized in colon cancer in 1979 and recently is known as a highly expressed antigen on a variety of carcinomas, thus, it is utilized as a carcinoma marker." (PMID 33182636, 2020). "Interestingly, it also blocks the sorting of EpCAM, a bona fide target used for carcinoma exosome immunocapture." (PMID 33343836, 2020). "Antagonizing antibodies such as EpAb2-6 and small molecule inhibitors that compete with EpCAM RIP or with EpICD functions could develop into promising candidate drugs for the treatment of EpCAM-positive carcinomas and the formation of lethal metastases." (PMID 32507912, 2020). "Over the past four decades, EpCAM has evolved from a humoral antigen expressed on the majority of carcinoma cells to a complex signaling molecule involved in central aspects of cell fate such as proliferation, pluripotency, differentiation, and organ integrity." (PMID 32507912, 2020). "EpCAM+ CTC detection also varies among different types of carcinoma." (PMID 32764280, 2020). "Recently, the prognostic value of EpCAM on cancer treatment has been reported in several types of tumors, however, the prognostic value of EpCAM after radiation therapy is unknown." (PMID 31361893, 2019). "Then, gene expression analyses demonstrate that EpCAM is decreased in mesenchymal-like cancers." (PMID 31225512, 2019). "The CellSearch® system enables validated and automated enrichment of EpCAM-positive cancer cells." (PMID 31514447, 2019). "To elucidate whether PKM2 loss in cancer cells is linked to the increase of CSC-like function, we next isolated EpCAM+Lgr5+ cells from polyps and cultured single Lgr5+ CSC without Wnt3a and R-spondin." (PMID 30996297, 2019). "Taken together, these findings depict an important role for EpCAM in the induction and/or maintenance of proliferation and cellular differentiation of progenitors, stem cells, induced pluripotent stem cells, cancer cells, and cancer stem cells." (PMID 31225512, 2019). "Further studies will focus on the molecular regulation of PCA cancer stemness by EpCAM." (PMID 30467381, 2019). "In the majority of cancer tissues, EpCAM is frequently overexpressed." (PMID 31225512, 2019). "One of the explanation might be that the bi-functional antibody has the ability to bind EpCAM expressing cancer cells as well as cytotoxic T cells." (PMID 31354723, 2019). "The prognostic value of EpCAM expression is dependent on the cancer type." (PMID 31225512, 2019). "However, results on cancer cell lines about EpCAM are also conflicting and seem to be context dependent." (PMID 31225512, 2019).
cancer (continued). "Together with the supposed necessity of EMT as a prerequisite for cancer dissemination, these results have raised doubt whether EpCAM-based capture is sufficient to escape all CTCs relevant to metastatic progression." (PMID 31225512, 2019). "Consistent with clinical data, we also found that a subpopulation of EpCAM-positive cancer cells manifests significantly a higher viability after cisplatin treatment by preventing chemotherapy induced-apoptosis, which is regulated by the EpCAM-Bcl-2 signaling axis, in in vitro assays." (PMID 31261739, 2019). "EpCAM overexpression is correlated with worse prognosis in some types of cancer." (PMID 31324239, 2019). "When spike-in HCT116 cells were prepared in leucocyte at 1:1,000,000 dilution, cancer cells could be identified with fluorescein isothiocyanate (FITC)-conjugated anti-EpCAM antibody." (PMID 30626171, 2019). "Finally, the confocal microscopy analysis demonstrated the presence in the CTC population of both EPCAM+ or pan-CK+ CD45− cancer cells and EPCAM+ or pan-CK+ CD45+ atypical CTCs." (PMID 31552188, 2019). "Investigating the dynamic range of EpCAM expression on CTC in different cancer entities might provide new insights in the biology of cancer metastasis." (PMID 31225512, 2019). "EpCAM is primarily considered as an adhesion molecule, but recent studies have shown diverse biological functions including regulation of cell proliferation and cancer stemness." (PMID 31225512, 2019). "Additionally, samples were counterstained with cancer-specific markers, such as cytokeratin or epithelial cell-adhesion molecule (EpCAM), to further support that the CD45 positive cells were most likely real TN-hybrids." (PMID 30736482, 2019). "The developed aptamer clones, EPCAM-APT-01 and EPCAM-APT-02, may be further used for EpCAM detection in real clinical samples in most human adenocarcinomas and it is a marker for cancer stem cells in several solid cancers." (PMID 30871104, 2019). "CellSearch capture reagent (unicapture) is based on EpCAM expression, a proven method of detecting CTCs; however, EpCAM CTC capture has the potential of missing cells that have, for example, undergone EMT, a process linked to cancer cell invasion and chemoresistance." (PMID 31215484, 2019). "In addition, in other studies, EpCAM was identified to be important for modulating the function of tight junctions, which is vital for metastasis of cancer cells via co-localization of selected claudins." (PMID 30289336, 2019). "A new electrochemical immunosensor for cancer cell detection based on a specific interaction between the metastasis-related antigen of epithelial cell adhesion molecule (EpCAM) on the cell membrane and its monoclonal antibody (Anti-EpCAM) immobilized on a gold electrode has been developed." (PMID 31010258, 2019). "EpCAM is mostly expressed in epithelial cells but likewise also expressed in various tissue stem cells, precursors, and in murine and human embryonic stem cells, which has important implications for cancer progression." (PMID 31225512, 2019). "Notably, DCA downregulated the expression of the cancer stem cells markers CD24/CD44/EPCAM only in PANC-1 but inhibited spheroid formation/viability in both cell lines." (PMID 31109089, 2019). "Our group has recently experienced the ability of DCA to reduce the expression of cancer stem cell markers CD24/CD44/EPCAM in a pancreatic cancer cell line as well as to compromise spheroid formation and viability, further corroborating data obtained in other cancer models." (PMID 31827705, 2019). "To identify genes that are deregulated in HCC, we analyzed differential gene expression in paired HCC and normal para‐carcinoma tissues in epithelial cell adhesion molecule (EpCAM)‐positive and EpCAM‐negative tumors, using GSE5975 profiles from the Gene Expression Omnibus database." (PMID 31267557, 2019).